BPNT1 (3'(2'), 5'-bisphosphate nucleotidase 1)
Description:
Phosphatase that converts 3'(2')-phosphoadenosine 5'-phosphate (PAP) to AMP and inositol 1,4-bisphosphate (Ins(1,4)P2) to inositol 4-phosphate. Is also able to hydrolyze adenosine 3'-phosphate 5'-phosphosulfate (PAPS) to adenosine 5'-phosphosulfate (APS) (By similarity). Probably prevents the toxic accumulation of PAP, a compound which inhibits a variety of proteins, including PAPS-utilizing enzymes such as sulfotransferases, and RNA processing enzymes. Could also play a role in inositol recycling and phosphoinositide metabolism. Is not active on 3'-AMP, inositol-1-phosphate and inositol-1,4,5-triphosphate.
Synonyms: HEL20; HsPIP; PIP
Tractability: Small molecule: a structure with a bound ligand is known; it has a high-quality binding pocket; it belongs to a druggable protein family. PROTAC: ubiquitination databases record sites on it; its protein half-life has been measured.
Target class: Enzyme; Hydrolase
Gene: Protein-coding gene on chromosome 1 (220,057,079 to 220,119,267, reverse strand). Ensembl gene ENSG00000162813.
Subcellular location (Human Protein Atlas): Nuclear speckles
Pathways (Reactome):
Metabolism: Cytosolic sulfonation of small molecules
Gene Ontology:
Molecular function: 3'(2'),5'-bisphosphate nucleotidase activity; inositol-1,4-bisphosphate 1-phosphatase activity
Biological process: 3'-phosphoadenosine 5'-phosphosulfate metabolic process; nervous system development; nucleobase-containing compound metabolic process; phosphatidylinositol phosphate biosynthetic process
Cellular component: mitochondrion; cytosol
Genetic constraint (gnomAD): Loss-of-function variants: 20 observed, 25.82 expected, observed/expected ratio (o/e) 0.77, 90% interval 0.54 to 1.12. The upper end of that interval is the gene's LOEUF score, 1.12, which puts it in group 4 of 6, group 1 being the genes least tolerant of losing a copy. Missense variants: 258 observed, 313.64 expected, observed/expected ratio (o/e) 0.82, 90% interval 0.74 to 0.91. Synonymous variants: 96 observed, 115.67 expected, observed/expected ratio (o/e) 0.83, 90% interval 0.7 to 0.98.
Homologues: Orthologues: chimpanzee BPNT1 (100% identical), macaque BPNT1 (99% identical), dog BPNT1 (95% identical), rabbit BPNT1 (94% identical), pig BPNT1 (94% identical), mouse Bpnt1 (92% identical), guinea pig BPNT1 (92% identical), rat Bpnt1 (91% identical), tropical clawed frog bpnt1 (81% identical), zebrafish bpnt1 (74% identical), Drosophila melanogaster CG7789 (50% identical), Caenorhabditis elegans bpnt-1 (44% identical). Paralogues in human: BPNT2 (30% identical), INPP1 (28% identical), IMPA1 (22% identical), IMPA2 (22% identical).
Diseases named in the same sentence as BPNT1 in open-access papers:
BPNT1 is named in the same sentence as 13 diseases in open-access papers, as found by Europe PMC text mining. Sharing a sentence is not in itself a finding about the gene and the disease. The quoted sentences say what the papers report.
breast carcinoma (2 papers, 2021 to 2026). "The adenosine at position 1894 in the BPNT1 mRNA was shown to be highly edited (∼75%) in four different breast cancer cell lines." (PMID 35586115, 2021).
bipolar disorder (1 paper, 2024). A disorder of the brain that causes unusual shifts in mood, energy, activity levels and the ability to carry out day-to-day tasks. "Although precise data about BPNT1 gene function is not available, It is highly expressed throughout the brain and is severely suppressed by lithium, a medication that is frequently used to treat bipolar disorder." (PMID 38308303, 2024).
epilepsy (1 paper, 2025). A brain disorder characterized by episodes of abnormally increased neuronal discharge resulting in transient episodes of sensory or motor neurological dysfunction, or psychic dysfunction. "There were 8 proteins shared between epilepsy and ischemic stroke: SH3BGRL3, BPNT1, PTPMT1, PACSIN3, MIPEP, CMC2, ABCA5, and PTK2B." (PMID 40624693, 2025).
glioma (1 paper, 2018). A benign or malignant brain and spinal cord tumor that arises from glial cells (astrocytes, oligodendrocytes, ependymal cells). "Therefore, it is reasonable to speculate that the deficiencies of IMPAD-1 and BPNT-1 function would lead to a lower degradation rate of pAp and hence promote its accumulation in glioma." (PMID 30283018, 2018). "The gene expressions of IMPAD-1 (gPAPP) and BPNT-1 were remarkably down-regulated in glioma, especially the former (more than 90% reduction)." (PMID 30283018, 2018). "Finally, we observed that gene expression levels of IMPAD1 and BPNT1 were significantly decreased in glioma tissues (p < 0.05)." (PMID 30283018, 2018).
hyperglycaemia (1 paper, 2020). "Our data also showed that hyperglycaemia induces a decrease of Bpnt1 protein expression correlated with renal tissue damage, data that concur with studies disclosing that the kidney proximal tubule epithelial cells are affected in the Bpnt1 knockout mouse." (PMID 32935914, 2020).
liver failure (1 paper, 2018). A liver disease characterized by the liver losing or has lost all of its function. "Loss of BPNT-1 function results in liver failure,whole-body edema and death, while the levels of bisphosphorylated nucleotides, pAp and PAPS, were dramatically elevated in the BPNT-1 mutant liver and neurons." (PMID 30283018, 2018).
cancer (2 papers, 2019 to 2026). A tumor composed of atypical neoplastic, often pleomorphic cells that invade other tissues. "It appears that the interactomes of five out of the 17 lithium-sensitive genes (ADCY2, ADCY5, ADCY7, BPNT1, and HIPK3) do not show significant mutual enrichment with the cancer pathways explored in this study." (PMID 31114752, 2019).
tumor (2 papers, 2025 to 2026). "Loss- and gain-of-function assays revealed that BPNT1 acted as a novel oncogenic driver to promote TNBC cell proliferation, migration, invasion in vitro and to accelerate xenograft tumor growth and lung metastasis in mice." (PMID 41540000, 2026). "Collectively, these genetic rescue experiments demonstrated that the tumor-promoting functions of BPNT1 in TNBC are largely dependent on the STUB1-mediated ubiquitination and degradation of LIMA1." (PMID 41540000, 2026). "Consistent with in vitro observations, BPNT1 knockdown suppressed tumor growth in vivo (volume, weight)." (PMID 41540000, 2026). "Our findings position BPNT1 as a novel molecular scaffold that redirects STUB1’s catalytic activity toward LIMA1 degradation, resolving its tumor-promoting role in TNBC." (PMID 41540000, 2026). "Collectively, these findings delineate a novel oncogenic axis wherein BPNT1 scaffolds STUB1-mediated ubiquitination and degradation of LIMA1, driving EMT-facilitated tumor progression and DTX chemoresistance." (PMID 41540000, 2026). "Collectively, these data demonstrate that BPNT1 scaffolds STUB1 recruitment to catalyze ubiquitin-dependent proteasomal degradation of LIMA1, thereby depleting this tumor suppressor in TNBC." (PMID 41540000, 2026).
genetic disorders (1 paper, 2023). "BPNT1 has not been linked to any genetic disorders to date, however, Bpnt1-/- mice develop severe liver damage which leads to whole-body edema and death." (PMID 37146074, 2023).
BPNT1 also shares sentences with these, for which no sentence is quoted: chondrodysplasia (1 paper); gastric cancer (1); ischemic stroke (1); metabolic disorders (1).